NOTCH1 (notch receptor 1)
Diseases named in the same sentence as NOTCH1 in open-access papers (continued):
Sharing a sentence is not in itself a finding about the gene and the disease.
leukemia (continued). "However, most gain-of-function NOTCH1 mutations found in human T-ALL do not generate downstream signals of sufficient strength to efficiently initiate leukemia development in mice." (PMID 28122332, 2017). "While inhibition of the NOTCH1 signaling pathway may be effective in eliminating ATL leukemia cells, this strategy may increase the SP cells and lead to disease relapse, suggesting that combination therapies targeting both cellular compartments may be more effective in curing ATL." (PMID 28920078, 2017). "Moreover, glutaminase inhibition synergized with NOTCH1 inhibition to inhibit leukemia growth." (PMID 28872614, 2017). "Furthermore, PRDM14 bound to a region within the fourth intron of Notch1 prior to leukemia onset, and may have promoted epigenetic changes that enhanced the accessibility of the Notch1 cRSSs to the RAG complex." (PMID 27106930, 2016). "Thus, Notch-1 positive leukemia cells were found to be targeted by L-fucose-bound liposomes." (PMID 27233074, 2016). "Thus, the expression of CD33 and Notch-1 correlated in the same leukemia cell lines." (PMID 27233074, 2016). "Our study of the network of Notch1 protein interactors has highlighted the possible interactions through which Notch signaling might lead to uncontrolled proliferation of cells leading to neoplastic transformation resulting in Leukemia." (PMID 24688641, 2012). "However, in leukemia, its not abberrent gene regulation that leads to constititutively active Notch-1 expression, its somatic activating mutations in the receptor which allows the receptor to have increase stability." (PMID 21637838, 2011). "In addition, tumor (7065) has insertions in Notch1 and Il2rg, suggesting that Il2rg might be able to cooperate with other T-cell oncogenes (i.e. Notch1) in leukemia induction." (PMID 19461887, 2009). "As expected, several previously reported genes with abnormal methylation in leukemias such as CPEB1, BLK, FLT3, ZCCHC7, EBF1, HDACs, IKZF1, RB1, CDK6, DOCK5, DPP10, MUC4, JAKs, KIT, KRAS, LINC01013, MAD1L1, NOTCH1, and STATs, among others, were also detected." (PMID 41226303, 2025). "Using RNA-Seq and RT-qPCR, we demonstrated that NOTCH1 and its respective target genes, such as HES1 and IGF1R, are upregulated and highly activated in MLLr leukemia cells." (PMID 37833915, 2023). "Biochemical assays were notable for showing activation of WNT, NOTCH1, TGFβ, RTK, and cytokine signaling pathways known to drive EMT in MSC-adherent leukemia cells." (PMID 37453060, 2023). "The results showed that leukemia burden decreased after the treatment of DEX, but the expression levels of DLL1 in adipocytes and the levels of Notch1 in T‐ALL cells around adipocytes were higher." (PMID 37072664, 2023). "In Notch1-driven T-cell acute lymphoblastic leukemia (T-ALL), we first noted that MBD2 is required for the progression and maintenance of leukemia." (PMID 37142578, 2023). "NOTCH1 is constitutively activated in a majority of T-ALL, including those that overexpress TAL1, and in leukemias from E2a-/- mice." (PMID 35514954, 2022). "The NOTCH1-MYC-CD44 axis integrates cell-intrinsic and extrinsic signaling to ensure the persistence of leukemia-initiating cells (LICs) in T-cell acute lymphoblastic leukemia (T-ALL) but a common pathway to target this circuit is poorly defined." (PMID 35173274, 2022). "Notch1 has been shown to directly activate expression of Insulin-like growth factor 1 receptor (IGF1R) in T-ALL, which contributes to leukemia survival through the PI3K/Akt pathway." (PMID 34394130, 2021). "However, we have demonstrated the SERCA inhibition may efficiently control the trafficking of NOTCH1 and that this blockade can be achieved without causing overt cardiac toxicities in preclinical leukemia models." (PMID 33407740, 2021).
leukemia (continued). "For example, inactivation of PHF6 in hematopoietic progenitors has been reported to facilitate NOTCH1-induced T-ALL, potentially through increasing leukemia-initiating cells and development of a “leukemia stem cell transcriptional program” in lymphoblasts." (PMID 34381727, 2021). "We previously found that CARMA1 is crucial for Notch1-induced NF-κB activation in T-ALL and contributes to Notch1-driven leukemia progression." (PMID 33072583, 2020). "Repeated cycles of 1 day fasting followed by 1 day of feeding shortly after transplantation of leukemia cells completely inhibited leukemia development in the N-Myc B-ALL model and massively decreased the leukemic burden in the Notch1 T-ALL model." (PMID 32474572, 2020). "We previously showed that these pre-LSCs are driven by the SCL/TAL1 and LMO1 oncogenes, which depend on NOTCH1-MYC pathways, and are resistant to chemotherapeutic drugs used against leukemia (doxorubicin, camptothecin and dexamethasone)." (PMID 31196146, 2019). "Our laboratory showed that oncogenic NOTCH1 regulates MYC expression and leukemia-initiating cell activity and demonstrated the efficacy of NOTCH1 inhibitors in pre-clinical T-ALL models." (PMID 30967879, 2018). "In an in vitro leukemia model, two BMI1 inhibitors, PTC-209 and PRT-4165, down-regulating the expression of NOTCH1, HES1, and c-MYC, were able to block the leukemic cells growth, suggesting that the BMI1 inhibitors can be good candidates against leukemia." (PMID 30574454, 2018). "IGF1R expression can be directly regulated by NOTCH1 and is important for T-ALL proliferation and leukemia initiating activity in vivo." (PMID 28872614, 2017). "The authors also report decreased NOTCH1 and NOTCH targets and increased NOTCH2 in the leukaemia initiating HSC population in an MLL-AF9 AML mouse model." (PMID 25711903, 2015). "NOTCH1 and NOTCH2 are involved in neoplastic disease, e.g. leukemia, skin cancers, in human medulloblastomas." (PMID 17593975, 2007). "Moreover, confirming the direct binding of TAL1 isoforms and NOTCH1 effectors to TSPAN32 regulatory elements, as well as determining the functional impact of TSPAN32 reactivation on leukemia cell behavior, will be critical next steps." (PMID 41007654, 2025). "Similarly, in leukemia, the interaction between ZMIZ1 and Notch1 enhances C-MYC transcription and activity, facilitating leukemia initiation and progression, while ZMIZ1 inhibition attenuates leukemia progression." (PMID 38866828, 2024). "Interestingly, upregulation of Olig2 alone is weakly oncogenic in leukemia, however, together with LMO1 and Notch1, overexpression results in cell proliferation." (PMID 37274223, 2023). "In SUP-T1 cells, apart from downregulation of the known BRD4 targets like Myc, Bcl-2, Bcl-XL, and Mcl-1, treatment with ARV-825 substantially decreased the expression of key molecules involved in leukemia persistence, such as HES1 (a direct target of Notch1), PI3K/AKT pathway proteins, and CD44." (PMID 35173274, 2022). "These involve genes which are known to be leukemia drivers (such as FAT1, NOTCH1, PHF6, FLT3), and can activate signaling pathways that push the cells to multiply faster, as well as genes involved in ribosome biogenesis or translational control (such as WDR36 and LTV1)." (PMID 36482893, 2022). "For example, CD34 was reported as a marker for T-LICs in xenografts from pediatric T-ALL, whereas in adult T-ALL-derived xenografts, the CD7+CD1a− but not the CD34+ subset initiates leukemia in response to NOTCH1 activation." (PMID 36428753, 2022). "By quantifying two disease endpoints, T-ALL penetrance and disease latency, i.e. the median time to overt leukemia, we show that in the context of the SCL and LMO1 oncogenes, the hyperactive Notch1 oncogene on its own determines disease penetrance even in the absence of pre-TCR signaling." (PMID 35401501, 2022).
leukemia (continued). "In addition, the pre-TCR signal is important for Notch1/ICN1, Notch3- and TEL-JAK2-induced leukemias, indicating that developmental processes required for normal thymocyte development can be implicated in the pathogenesis of T-ALL." (PMID 35401501, 2022). "All NOTCH1-signaling-dependent T-ALL cell lines were sensitive to MRK-560 and its combination with ruxolitinib or imatinib in JAK1- or ABL1-dependent cell lines synergistically inhibited leukemia proliferation." (PMID 34167562, 2021). "Yet, our data show that loss of NFAT1 function does not affect leukemia onset and outcome in T-ALL induced in mice by activated NOTCH1 (ICN1) or activated JAK2 (TEL/ETV6-JAK2), indicating lack of tumor suppressive function of Nfat1 in early T cell progenitors." (PMID 34234374, 2021). "With the aim to establish a functional relationship between constitutive NOTCH1 signaling and ARF deletion in T-ALL, the hypothesis developed above was tested in NOTCH1-dependent T-ALL leukemias generated in mouse models." (PMID 33435487, 2021). "By contrast, mice transplanted with D1 cells overexpressing NRARP alone developed leukemia with similar kinetics to those transplanted with D1 NICD1 cells, confirming the oncogenic potential of NRARP in the context of low levels of Notch1 signaling." (PMID 31586130, 2020). "In keeping with these findings, in this work, we observed that Notch3 (but not Notch1) is able to interact with GRP78/Bip in leukemia cells in basal conditions." (PMID 33071287, 2020). "All of the T-ALL xenograft mice carrying NOTCH1-mutant had reduced circulating leukemia cells, while the animals carrying NOTCH1 wild-type had no response to OMP-52M51 treatment." (PMID 33292596, 2020). "These last findings further indicate c-Myc as a prominent mediator of Notch oncogenic function that is consistent with the essential role of c-Myc in Notch1-driven leukemia and with its property to rescue T-ALL cells from the anti-growth effects of Notch1 inhibition by GSI treatment." (PMID 31001470, 2019). "Moreover, we applied the same strategy to two additional mouse models of leukemia, mice that received MLL-NRIP3 AML cells or Notch1 T-cell acute lymphoblastic leukemia (T-ALL) cells, and observed a similar high survival rate." (PMID 31811153, 2019). "Correspondingly, Topo1 inhibitor selectively eradicates Notch1-driven AtmKD/- leukemia, but not the isogenic parental Atm proficient leukemia, identifying Topo1 inhibitors as a targeted therapy for human cancers carrying missense ATM kinase domain mutations." (PMID 27304073, 2016). "Using these Fuc-Liposomes, we added FAM encapsulated L-fucose-liposomes (Fuc-Liposome-FAM) to Notch-1 positive or negative leukemia cell lines to confirm the specificity of delivery." (PMID 27233074, 2016). "Indeed, breeding into a RAG recombination-deficient background abrogates T-ALL development and prevents Notch1 deletions, while allowing for transient hematopoietic stem cell (HSC)-like pre-leukemia cell expansion." (PMID 27106930, 2016). "We examined the effect of Fuc-Liposome-daunorubicin on leukemia patients' Notch-1 positive and negative cells." (PMID 27233074, 2016). "F50-Liposomes containing daunorubicin effectively suppressed Notch-1 positive cells but not negative cells, indicating that fucose bound-liposomes specifically targeted Notch-1 positive leukemia cells isolated from patients." (PMID 27233074, 2016). "In this study, we used the Notch1-induced mouse T-ALL model to compare the effects of the BM and spleen environments on a number of biological features, such as homing, proliferation and migration, of disseminated leukemia cells." (PMID 25366136, 2014). "In leukemia cells from patients, four AML samples expressed Notch1 and/or Jagged1." (PMID 23181106, 2012).
leukemia (continued). "In agreement with this hypothesis, several of the genes identified in our analysis have been suggested to be putative therapeutic targets in leukemia, with either preclinical or clinical trials underway (CDK4, CDK6, GSK3b, MYC, LCK, NFkB2, BCL2L1, NOTCH1)." (PMID 21356087, 2011). "Indeed, in E2a-/- leukemias c-MYC expression is stably amplified through trisomy at chromosome 15 and therefore does not require ICN for expression yet these leukemias are still dependent on Notch1 signaling." (PMID 35514954, 2022). "We showed here that unlike LEF1, TCF1 is not regulated by Notch signaling in E2a-/- leukemias and therefore we hypothesize that Notch1 regulates Lef1 directly and independent of TCF1." (PMID 35371057, 2022). "Indeed, mice overexpressing NOTCH1 fail to develop leukemia when lacking functional ETS1 suggesting that both of these factors are required for leukemia initiation." (PMID 35514954, 2022). "Importantly, expression of the most frequently mutated genes in T cell lymphoma or leukemia (i.e., DNMT3A, TET2, JAK, NOTCH1, CDKN2A, PTEN, and FBXW7) was not altered in miR-H18-BCMA CAR T cells." (PMID 35821635, 2022). "In addition to gastrointestinal toxicity and limited anti-leukemia effects, researchers also found that there are differences in the degree of inhibition of NOTCH1 cleavage by various GSIs and a lack of bioequivalence." (PMID 33292596, 2020). "In addition to Hox genes, Pim1, Notch1, and downregulation of INK4A-ARF by Bmi-1 have also been shown to cooperate with E2A-PBX1 in oncogenesis suggesting the importance of secondary hits in the development of E2A-PBX1 driven leukemias." (PMID 24847444, 2014). "Therefore, we aimed to detect Notch1 and Jagged1 in non-permeabilised cells using leukemia/lymphoma cell lines in which Notch1 and Jagged1 expression had been examined by immunoblot analysis." (PMID 23181106, 2012). "Interestingly, among them, we found miR-709 and miR-29, which have already been described as tumor suppressors in T-ALL, and miR-22-3p, which has a known tumor suppressor function in different tumor contexts but has not yet been investigated in NOTCH1-induced leukemia." (PMID 32708470, 2020). "While our in vitro study showed promising results in blocking NOTCH1 signaling using the therapeutic CAD204520, the use of monotherapies is unlikely to cure leukemia due to tumor heterogeneity and acquired resistance." (PMID 37833915, 2023). "Leukemia induction by NOTCH1 requires synergistic signaling through the pre-TCR complex, as constitutively active NOTCH1 alone does not induce leukemia in Rag2−/− or Ptcra−/− mice." (PMID 36765626, 2023). "Although NOTCH3 is assumed as a Notch1 target, machinery driving its transcription in T-ALL is undefined in leukemia subsets lacking Notch1 activation." (PMID 31001470, 2019). "Although no direct relationship between Notch 1 and CREB has been reported in leukemia to date, Notch regulates the phosphorylation of CREB involved in long-term memory formation in Drosophila melanogaster." (PMID 26008971, 2015). "Although the induction of NOTCH1 degradation may play a major role, we could not rule out the possibility that other USP7 substrates also contribute to the anti-leukemia effects upon USP7 inhibition." (PMID 30370059, 2018). "Indeed, introducing the Notch1/IC oncogene that drives elevated and activated NOTCH1 in thymocytes is sufficient to transform SCL-LMO1-induced pre-LSCs into hypercompetitive leukemia-propagating cells and to trigger aggressive T-ALL without latency." (PMID 35589701, 2022). "Although the detection of Notch1 protein in acute lymphoblastic leukemia cells using immunoblot analysis has been previously reported, the expression patterns of Notch1 and Jagged1 detected by flow cytometry (FCM) in normal blood cells and various leukemia cells have not been well-characterised." (PMID 23181106, 2012).
T-cell acute lymphoblastic leukemia (175 papers, 2008 to 2026). Acute lymphoblastic leukemia of T-cell origin. "Aberrant Notch signalling due to genetic mutations that occur within the negative regulatory region of the Notch 1 gene is linked to the development of acute T-cell leukaemia in humans." (PMID 41603691, 2026). "In fact, internal tandem duplication around exon 28 in NOTCH1, which is frequently observed in T-cell acute lymphoblastic leukemia patients, is known to cause ligand-independent NOTCH1 activation by expanding the extracellular juxtamembrane region." (PMID 39788962, 2025). "T-cell acute lymphoblastic leukaemia (T-ALL) is a haematological malignancy commonly driven by NOTCH1 activating mutations." (PMID 41120088, 2025). "BRON was designed to recognize the Negative Regulatory Region (NRR) of Notch1, which is the region where gain-of-function mutations have been reported in 50% of T cell acute lymphoblastic leukemia (T-ALL)." (PMID 39491031, 2024). "Mutations in the signaling and transcriptional regulator Notch1 result in various developmental aortic valve abnormalities, severe valve calcification, and T-cell acute lymphoblastic leukemia." (PMID 38790158, 2024). "Notch1 is one of the most frequently mutant genes in T cell acute lymphoblastic leukemia (T-ALL), and more than 50% of cases harbor active mutations of Notch1." (PMID 38933287, 2023). "T-cell acute lymphoblastic leukemia (T-ALL) is commonly driven by activating mutations in NOTCH1 that facilitate glutamine oxidation." (PMID 35589701, 2022). "In T-cell ALL, the three most frequently mutated genes were NOTCH1 (37.5%), FBXW7 (16.6%), and PTEN (6.2%)." (PMID 36362526, 2022). "NOTCH1 gain of function mutations invariably lead to T-cell acute lymphoblastic leukemia (T-ALL), whereas inhibition of E proteins accelerates leukemogenesis." (PMID 35401501, 2022). "Mutations in the NOTCH1 gene are associated with aortic valve disease, Adams-Oliver syndrome, T-cell acute lymphoblastic leukemia, chronic lymphocytic leukemia, and head and neck squamous cell carcinoma." (PMID 36268024, 2022). "In fact, constitutive activation of NOTCH1 signaling is the most prominent oncogenic pathway during T-cell transformation in more than 60% of all human T-cell acute lymphoblastic leukemia cases, which are mainly caused by different activating mutations." (PMID 36059467, 2022). "In fact, more than 50% of cases of human T cell acute lymphoblastic leukemia (T-ALL) are associated with activating mutations in NOTCH1, with the majority of these affecting the NRR." (PMID 34555015, 2021). "NOTCH1 is a master regulator of T cell maturation; besides its aberrant activation of NOTCH1 is a hallmark of T cell acute lymphoblastic leukemia and it is found mutated in at least 65% of cases." (PMID 32436933, 2021). "Gain-of-function mutations in Notch1 are hallmark driver mutations in T-cell acute lymphoblastic leukemia (T-ALL) leading to ligand-independent Notch1 signaling." (PMID 34572582, 2021). "This prevalence was different from those reported in T-cell acute lymphoblastic leukemia and chronic lymphocytic leukemia, in which more than half the cases displayed NOTCH-1 mutations." (PMID 32711424, 2020). "NOTCH-1 was discovered to be upregulated in Hodgkin’s lymphoma, and its mutations were spot to serve as secondary events in some T-cell acute lymphoblastic leukemia sufferers." (PMID 32655137, 2020). "NOTCH1 is an oncogene, most notably, NOTCH1 mutations are present in the majority of patients with T cell acute lymphocytic leukemia." (PMID 33717054, 2020). "Constitutive NOTCH1 signaling, mainly through NOTCH1 activating mutations or mutations affecting NOTCH1 pathway regulators, are observed in over 60% of all T cell acute lymphoblastic leukemia (T-ALL) cases." (PMID 33251223, 2020). "Apart from activating mutations of Notch1 in T-cell acute lymphoblastic leukemia (T-ALL), somatic mutations in Notch1, 2, 3, and 4 genes in common solid cancers are rare." (PMID 32211044, 2020).